BDNF (brain derived neurotrophic factor)
Diseases named in the same sentence as BDNF in open-access papers (continued):
Sharing a sentence is not in itself a finding about the gene and the disease.
autism (continued). "The lack of effect on autism symptoms in this trial might have been due to the possibility that MMP activation and BDNF upregulation during the early stage may induce autism phenotypes, but BDNF upregulation at later stages may not play a large role in the maintenance of autism phenotypes." (PMID 27352957, 2016).
Insulin resistance (125 papers, 2010 to 2026). Increased resistance towards insulin, that is, diminished effectiveness of insulin in reducing blood glucose levels. "One study showed that the Brain-Derived Neurotrophic Factor (BDNF) 196G > A rs6265 polymorphism showed a statistically significant association with insulin resistance." (PMID 41009999, 2025). "HFD induced a decrease in hippocampal BDNF, which was associated with hippocampal neuroinflammation and insulin resistance." (PMID 40526304, 2025). "Since the associations have not yet been assessed and replicated in other studies, further studies are needed to confirm the associations of BDNF or LEP genetic variants with insulin resistance/weight gain in ASD patients treated with risperidone." (PMID 38375208, 2023). "Previous human research has shown that low circulating concentrations of BDNF are associated with insulin resistance, type 2 diabetes, and cognitive impairments." (PMID 37237034, 2023). "Impairment in glucose regulation have also been observed in humans carrying BDNF Met variant that show insulin resistance and increased risk for metabolic disorders." (PMID 35296634, 2022). "Obese patients with BDNF variants presented mild to severe hyperphagia and insulin resistance with dyslipidaemia in two cases." (PMID 30926952, 2020). "On the other hand, BDNF was positively correlated with numerous metabolic risk factors (i.e., increased triglyceride, glucose, and HbA1C, as well as insulin resistance, in the bloodstream)." (PMID 33375318, 2020). "Insulin resistance and other risk factors of MetS are negatively associated with BDNF, the critical mediator of neuronal vitality and function that regulates hippocampal neurogenesis and cognitive performance." (PMID 31700717, 2019). "A large body of evidence, both in animals and humans, supports the association between serum BDNF and insulin resistance and glucose metabolism." (PMID 29028824, 2017). "Among the baseline characteristics assessed in the present study, only fasting insulin and insulin resistance (presented by HOMA-IR) were significantly associated with increase in BDNF." (PMID 24524285, 2014). "This has been described by others in BDNF HETs previously, and was associated with hyperphagia, hyperglycemia, insulin resistance, and hypoactivity." (PMID 23781174, 2013). "An insulin resistance state or T2D profile are associated with a low concentration of BDNF." (PMID 40943107, 2025). "These observed associations between BDNF DNA methylation patterns suggest that BDNF may be involved in the pathophysiological process of insulin resistance and T2DM." (PMID 35225959, 2022). "Therefore, the question now is how to explain the earlier findings showing that insulin resistance or higher glucose levels in diabetic patients is associated with lower circulating BDNF concentrations in both serum and plasma." (PMID 34992516, 2021). "Acting as a regulatory pathway, plasma BDNF synthesis could be thus upregulated in some people with AD in order to try to counteract and compensate the insulin resistance and neuronal loss, independently of the illness severity and associated treatments." (PMID 31921371, 2020). "Consistent with animal models, plasma BDNF levels have previously been reported to be inversely correlated with fasting plasma glucose among type 2 diabetes patients and to be associated with the severity of insulin resistance." (PMID 21912638, 2011). "Besides, BDNF has been reported to be positively correlated with numerous metabolic risk factors such as increased circulating levels of triglyceride, glucose, and HbA1C and insulin resistance." (PMID 33375318, 2020). "A diet high in saturated fat and refined carbohydrates may cause insulin resistance, reduce BDNF and other neurotrophin concentrations, and thereby impair synaptic plasticity and neurogenesis in the hippocampus, increase neuroinflammation, and alter the blood–brain barrier." (PMID 32033054, 2020).
Insulin resistance (continued). "Therefore, BDNF, systematic inflammation, and insulin resistance are potential putative mechanisms that could causally link physical activity with cognition in cancer survivors." (PMID 31605514, 2019). "Hippocampal BDNF is not only related to cognitive functions, including learning and memory, but is also associated with insulin resistance, and it also improves glucose homeostasis and insulin resistance in obese, diabetic mice by decreasing food intake and blood glucose levels." (PMID 31311133, 2019). "Clinical studies have found reduced serum andplasma BDNF levels in type 2 diabetes patients, with changes in BDNF levelsnegatively correlated with insulin resistance." (PMID 41523972, 2025). "Among these, insulin resistance, a core feature of T2DM, has been shown to be significantly associated with circulating BDNF levels." (PMID 40933306, 2025). "Irisin is a hormone that enhances learning and memory by promoting brain-derived neurotrophic factor (BDNF), suppressing neuroinflammation, and improving insulin resistance and glucose homeostasis." (PMID 39594648, 2024). "Insufficient levels of BDNF can hinder the body’s glucose metabolism and insulin sensitivity, potentially contributing to the development of insulin resistance." (PMID 38773479, 2024). "Glucose intolerance and insulin resistance were more severe in Sh2b1ΔSIM1 than in Sh2b1f/f mice after BDNF expression." (PMID 38885417, 2024). "Reversion to the ND improved insulin resistance and lipid profile, besides brain-derived neurotrophic factor (BDNF), glycogen synthase kinase-3 beta (GSK3β), and insulin-degrading enzyme (IDE) levels." (PMID 39204160, 2024). "Lower BDNF levels have been shown to be correlated with worse delayed memory in T2DM, and there is evidence that decreased insulin resistance is associated with increased release of BDNF." (PMID 36970903, 2023). "In obese mice, administration of a BDNF mimetic suppresses lipid accumulation in the liver and improves insulin resistance." (PMID 35998179, 2022). "Regarding the motion pathways, insulin resistance is the key factor in the incidence of visceral obesity and low serum BDNF concentrations." (PMID 36185667, 2022). "It would be interesting to explore the role of BDNF in metabolic disorders, including insulin resistance and glucose intolerance that have been reported in ALS patients." (PMID 34411281, 2021). "The role of BDNF is complex since it can modulate insulin resistance and liver disease in animal models and is found in higher liver levels in those with cirrhosis and alcohol-induced injury." (PMID 34248683, 2021). "The administration of metformin (a medicine that decreases insulin resistance) stimulated an increased release of BDNF into the serum." (PMID 32012942, 2020). "Some ATF2 target genes, for example, BDNF and PEA15, are also linked to the development of insulin resistance under glucose stimulation." (PMID 32993798, 2020). "BDNF improves blood glucose and insulin resistance as well as hepatomegaly and inflammation in db/db mice." (PMID 32175323, 2020). "Other ATF2 target genes BDNF downregulation and PEA15 upregulation are also linked to the development of insulin resistance under glucose stimulation, pathophysiology of type II diabetes mellitus." (PMID 32993798, 2020). "So, it can also be considered if hsa-miR-933 can reverse the effect of insulin resistance in response to glucose stimulus by upregulating BDNF." (PMID 32993798, 2020). "Rs11030104 in gene BDNF (OR = 1.18, 95% CI: 1.01–1.39) with insulin resistance was found, which disappeared after adjusting for covariates (p = 0.184)." (PMID 32260174, 2020). "BDNF inversely correlates with fasting plasma glucose and homeostasis model assessment of insulin resistance score (HOMA-IR), which is an indirect measure of IR." (PMID 31798417, 2019).
Insulin resistance (continued). "Mechanistically, the improved behavioral tests are associated with a reversal of brain insulin resistance and signs of brain inflammation observed in DIO mice, as well as changes in brain metabolites, some neurotransmitters and the neurotrophic factor BDNF." (PMID 29910467, 2018). "In this study, we found altered mediators implicated in insulin resistance and cognition, including adiponectin, PPARγ, ERK1/2, p66Shc, SIRT1 and BDNF." (PMID 29340106, 2017). "Other studies showed that BDNF improved hepatic insulin resistance in diabetic animals and that BDNF was positively correlated with triglyceride, total cholesterol, and LDL-C in humans." (PMID 25587547, 2014). "In animals, BDNF is involved in insulin resistance, reduces food intake, and lowers blood glucose levels in obese diabetic mice." (PMID 23766563, 2013). "The high-sucrose compared with control diet induced insulin resistance, and increased phosphorylated-cPLA2 protein, cPLA2 and iPLA2 activity and 12-lipoxygenase mRNA, but decreased BDNF mRNA and protein, and drebrin mRNA." (PMID 23110484, 2012). "This may be the result of impaired insulin resistance and glucose metabolism affecting BDNF expression." (PMID 40405549, 2025). "Interestingly, upregulation of muscle BDNF was associated with decreased insulin resistance (i.e., HOMA2-IR), suggesting a potential insulin-sensitizing effect of BDNF." (PMID 40171198, 2025). "In parallel, neuronal damage may also follow the development of insulin resistance and the reduction in sensitivity to neurotrophic factors, such as brain-derived neurotrophic factor (BDNF)." (PMID 40564047, 2025). "BDNF is also named “metabokine” because of its effects on glycemia, lipid profile and energy homeostasis beside its role in metabolic control, especially glucose metabolism and insulin resistance." (PMID 40088335, 2025). "Our results not only confirm the potential role of TIR in the activation of the pAkt/CREB/BDNF downstream signaling cascade but also support its role in neuroprotection and in the prevention of the deleterious effect of hyperglycemia and insulin resistance on the mentioned pathways." (PMID 38287296, 2024). "It seems that insulin resistance and fat accumulation are related to low levels of serum BDNF." (PMID 36185667, 2022). "Insulin resistance may also indirectly result in the adverse impact on synaptic plasticity by reducing the brain-derived neurotrophic factor (BDNF), eventually leading to the decline of cognitive and memory function." (PMID 35745162, 2022). "In particular, these authors reported that while maternal obesity induced insulin resistance and aberrant brain-derived neurotrophic factor (BDNF) signaling in the hippocampus of neonatal and adult offspring, these effects were counteracted by maternal MFGM administration." (PMID 35956326, 2022). "Additionally, insulin resistance and raised post-prandial glucose would directly inhibit the BDNF secretion." (PMID 36185667, 2022). "Taken together, BDNF may have been upregulated in this study as a compensatory mechanism to improve metabolic dysfunction and insulin resistance in patients with NAFLD who have a reduction in activity." (PMID 34440543, 2021). "Interestingly, plasma BDNF concentrations were negatively correlated with insulin resistance using the homeostatic model assessment version 2 (HOMA2-IR), but not with insulin concentrations." (PMID 34992516, 2021). "In summary, decreased insulin resistance stimulates the increased release of BDNF into the serum." (PMID 32012942, 2020). "BDNF has been reported to improve hepatic insulin resistance in obese rats." (PMID 32679912, 2020). "Thus, the amount of data about the role of BDNF in metabolic control, especially glucose metabolism and insulin resistance, is still increasing." (PMID 32012942, 2020).
Insulin resistance (continued). "BDNF has been shown to decrease appetite, increase energy expenditure, reduce body weight, and improve hyperglycemic conditions through ameliorating hepatic insulin resistance in animal models." (PMID 32210348, 2020). "Previous studies on model animals had demonstrated that BDNF may suppress food uptake, improve insulin resistance and maintain glucose homeostasis." (PMID 28056856, 2017). "One possibility is that the anti-inflammatory actions of resolvins and protectins can suppress the peripheral insulin resistance seen in type 2 DM and/or able to trigger the production of other antidiabetic molecules, such as brain-derived neurotrophic factor (BDNF)." (PMID 28824543, 2017). "Moreover, BDNF was inversely correlated with fasting plasma glucose and homeostasis model assessment of insulin resistance score (HOMA2-IR), which is an indirect measure of insulin resistance." (PMID 29062839, 2017). "In animal experiments, it is shown that, by suppressing PPAR-alpha and fibroblast growth factor 21, BDNF might facilitate insulin resistance and dyslipidemia and thus has antidiabetic and lipid lowering effects." (PMID 25587547, 2014). "Similar findings have been reported in non-diabetic individuals in which lower serum BDNF levels have been associated with insulin resistance and higher body fat." (PMID 22880108, 2012). "Furthermore, modulation of glucocorticoid signaling, cAMP metabolism and BDNF activity are connected with insulin resistance in humans and various animal models." (PMID 20353613, 2010). "Interestingly, in animal models, the over-expression of BDNF was shown to improve glucose metabolism and alleviate insulin resistance by suppressing the hyperglycemia-induced neuroinflammation in the hippocampus of type 1 diabetes mice through blocking the HMGB1/RAGE/NF-κB signaling pathway." (PMID 35682821, 2022). "BDNF may have a positive impact on the effect of insulin resistance." (PMID 32012942, 2020). "This may be due to increased insulin resistance results in disturbed cellular metabolism and increased oxidative stress, which could lead to dysregulation in the release of various neurotransmitters and growth factors, including BDNF." (PMID 33457130, 2020). "An intriguing hypothesis is that both systemic HFD-dependent insulin resistance and BDNF deficit are involved in the mother to offspring transmission of HFD-dependent cognitive impairment by changing the chromatin remodelers’ recruitment on Bdnf regulatory sequences." (PMID 31641124, 2019). "Therefore, BDNF may be one of the common pathways mediating both neurogenesis in the hippocampus and systemic metabolic process, such as insulin resistance." (PMID 21837282, 2011). "Higher DI‐GM scores were significantly associated with lower BMI, improved lipid profiles (↑ HDL‐C: β = 0.41; 95% CI: 0.39–0.44), reduced insulin resistance (↓ HOMA‐IR: β = −2.11; 95% CI: −2.15 to −2.07), and increased BDNF (β = 0.25; 95% CI: 0.19–0.30)." (PMID 41142011, 2025). "Neuronal insulin resistance disrupts long-term potentiation (LTP) which is critical for learning and memory, and decreases brain-derived neurotrophic factor (BDNF) resulting in neurodegeneration." (PMID 41169480, 2025). "An intriguing aspect of brain insulin resistance in AD is the interplay between insulin/p-IRS/PI3K/Akt signaling and the upregulation of BDNF." (PMID 39769243, 2024). "That is, when insulin resistance occurs in SCs, the expression of neurotrophic factors including CTNF, NGF, NT-3, BDNF is significantly suppressed, and the expression of myelination proteins is also decreased." (PMID 36291547, 2022). "Insulin resistance in the brain disrupted the NMDA receptor phosphorylation and final the production of BDNF." (PMID 34108878, 2021).
Insulin resistance (continued). "HFD has also been shown to negatively affect BDNF levels in the hippocampus, accompanying learning and memory deficits in the MWM task in female rats, and induce inflammatory responses and insulin resistance in the hippocampi of juvenile male mice given a HFD." (PMID 33669543, 2021). "It has been shown that insulin resistance, induced by chronic exposure to a HFD promotes short-term memory impairments and decreases brain-derived neurotrophic factor (BDNF) and phospho-Akt levels in the prefrontal cortex and hippocampus." (PMID 33967682, 2021). "It suppressed insulin resistance and enhanced insulin sensitivity and increased plasma LXA4 and BDNF levels and pancreas, brain, liver, and intestine BDNF concentrations." (PMID 33546300, 2021). "Fasting plasma insulin (10.6 ± 7.1 vs. 13.7 ± 17.8 μIU/mL, p = 0.021) and homeostatic model assessment of insulin resistance (HOMA-IR) index (2.6 ± 1.8 vs. 3.4 ± 5.6, p = 0.039) were significantly lower in the low BDNF group than in the high BDNF group." (PMID 32679912, 2020). "GDNF, CNTF, BDNF, and NRG4 improve insulin resistance and alleviate hepatic steatosis by reducing hepatic lipogenesis and improving β-oxidation." (PMID 32175323, 2020). "The concentration of BDNF correlates positively with immunoreactive insulin and HOMA-IR (homeostatic model assessment for insulin resistance) in women with type 2 diabetes." (PMID 32012942, 2020). "We examined several clinical parameters shown to be involved in nocturnal hypertension, including LVEF, eGFR, insulin resistance index HOMA, plasma aldosterone, plasma rennin activity, plasma BDNF, urinary cortisol, and urinary sodium output." (PMID 27166822, 2016). "Based on the regression model, the increase in BDNF was an independent factor for the reduction of Zung SDS, after adjusting for age, insulin resistance, and changes in weight." (PMID 24524285, 2014). "Consistent with another study, we observed a drop in BDNF concentration in the third trimester in women with T1DM, which could be explained by the physiologic increase of insulin resistance in the second half of the pregnancy." (PMID 40698658, 2025). "Compliant CPAP therapy was associated with reduced insulin resistance and no further BDNF increase, in contrast to non-compliance, suggesting a beneficial effect of CPAP on glucose metabolism and BDNF regulation." (PMID 40565316, 2025). "Other pharmacodynamic targets, such as brain-derived neurotrophic factor (BDNF) and leptin (LEP), may also be involved in risperidone-induced insulin resistance." (PMID 38375208, 2023). "Collectively, it is our interpretation that we did not observe any relationship between body composition values and cognitive scores or BDNF due to not studying individuals presenting with insulin resistance." (PMID 36092801, 2022). "In this study, a diet-induced decrease in brain derived neurotrophic factor (BDNF) was also evidenced, and the authors supposed a negative control exerted by insulin resistance on BDNF expression." (PMID 33374894, 2020). "It is worth mentioning that BDNF administration exerted anorectic effects on HFD-fed mice but without significantly interfering with peripheral insulin resistance nor counteracting IRS1 inhibition in the ovaries." (PMID 31641124, 2019). "It is possible that the increase recorded in BDNF in the current study of T2DM may compensate for hyperinsulinemia and insulin resistance." (PMID 25587547, 2014). "Additionally, clinical observations have revealed a significant negative correlation between hyperglycemia and insulin resistance severity and circulating BDNF levels." (PMID 40933306, 2025). "Furthermore, the absence of BDNF impairs mitochondrial function, leading to insulin resistance and increased adiposity." (PMID 39937973, 2025). "However, in female mice, a lack of BDNF resulted in skeletal muscle metabolic myopathy and insulin resistance." (PMID 31635145, 2019).
Insulin resistance (continued). "Therefore, due to the negative effect of insulin resistance and other mentioned metabolic disorders on serum BDNF levels, DII and DIL would be inversely related to serum BDNF levels." (PMID 36185667, 2022).